MLIP (muscular LMNA interacting protein)
Description:
Required for myoblast differentiation into myotubes, possibly acting as a transcriptional regulator of the myogenic program (By similarity). Required for cardiac adaptation to stress through integrated regulation of the AKT/mTOR pathways and FOXO1. Regulates cardiac homeostasis and plays a role in the protection against cardiac hypertrophy (By similarity). Binds chromatin (By similarity). May act as a transcriptional cofactor for ISL1, repressing its transcriptional activity (By similarity). May also repress MYOCD transcriptional activity (By similarity).
Synonyms: CIP; C6orf142; MGC18257; MMCKR; LOC101927189; MLIP-IT1
Tractability: Antibody: UniProt places it where antibodies can reach, with medium confidence; its Gene Ontology location is reachable by antibodies, with medium confidence; the Human Protein Atlas places it where antibodies can reach. PROTAC: its protein half-life has been measured.
Gene: Protein-coding gene on chromosome 6 (53,929,982 to 54,266,946, forward strand). Ensembl gene ENSG00000146147.
Subcellular location: Nucleus; Nucleus envelope; Nucleus, PML body; Cytoplasm, cytosol; Cell membrane, sarcolemma
Subcellular location (Human Protein Atlas): Nucleoplasm; Plasma membrane; Vesicles
Gene Ontology:
Biological process: negative regulation of cardiac muscle hypertrophy; negative regulation of cardiac muscle hypertrophy in response to stress; negative regulation of transcription by RNA polymerase II; positive regulation of transcription by RNA polymerase II
Cellular component: nucleus; nuclear envelope; nuclear lumen; PML body; sarcolemma; cytosol
Genetic constraint (gnomAD): Loss-of-function variants: 57 observed, 64.61 expected, observed/expected ratio (o/e) 0.88, 90% interval 0.71 to 1.1. The upper end of that interval is the gene's LOEUF score, 1.1, which puts it in group 4 of 6, group 1 being the genes least tolerant of losing a copy. Missense variants: 1,113 observed, 1,074.4 expected, observed/expected ratio (o/e) 1.04, 90% interval 0.99 to 1.09. Synonymous variants: 460 observed, 440.73 expected, observed/expected ratio (o/e) 1.04, 90% interval 0.97 to 1.13.
Homologues: Orthologues: chimpanzee MLIP (99% identical), macaque MLIP (96% identical), dog MLIP (82% identical), rabbit MLIP (77% identical), pig MLIP (71% identical), rat Mlip (70% identical), mouse Mlip (69% identical), tropical clawed frog MLIP (26% identical), guinea pig Mlip (20% identical), zebrafish mlip (10% identical).
Diseases named in the same sentence as MLIP in open-access papers:
MLIP is named in the same sentence as 20 diseases in open-access papers, as found by Europe PMC text mining. Sharing a sentence is not in itself a finding about the gene and the disease. The quoted sentences say what the papers report.
heart failure (4 papers, 2017 to 2024). Inability of the heart to pump blood at an adequate rate to meet tissue metabolic requirements. "MLIP has been proposed as a key regulator of cardiomyopathy and is reported to have a potential as a therapeutic target to attenuate heart failure progression." (PMID 33452295, 2021). "MLIP has recently been shown to be a key regulator of cardiomyopathy that has potential as a therapeutic target to attenuate heart failure progression." (PMID 28296976, 2017).
rhabdomyolysis (3 papers, 2022 to 2024). Necrosis or disintegration of skeletal muscle often followed by myoglobinuria. "Recently, the MLIP gene was identified as responsible for rhabdomyolysis, and decreased overall RNA expression levels of major MLIP isoforms were observed in the skeletal muscle of patients." (PMID 36213445, 2022).
breast carcinoma (2 papers, 2021 to 2024). "MLIP was identified as one of six genes associated with the breast cancer risk and recurrence-free survival." (PMID 38994962, 2024). "Specifically, Kumaran and colleagues reported that a loss in MLIP CNVs was associated with significant reduction in the breast cancer risk and recurrence-free survival, with a reported hazard ratio of 0.62 [0.4–0.94]." (PMID 38994962, 2024). "Our investigation identified two primary types of cancers where MLIP’s role was emphasized: breast cancer and esophageal cancer." (PMID 38994962, 2024). "As GALNTL5, MLIP, HMCN2, LRRN4CL and DUOX2 were identified as cytotoxicity-associated genes, we next investigated their effects on therapeutic response by analyzing RNA-seq data and drug sensitivity of multiple breast cancer cell lines using Pearson coefficient analysis." (PMID 35046993, 2021). "(F-J) Survival analysis was performed for GALNTL5, MLIP, HMCN2, LRRN4CL and DUOX2 using log-rank test for RNA-seq data and the corresponding survival data from the TCGA cohort of patients with breast cancer." (PMID 35046993, 2021).
cardiac hypertrophy (2 papers, 2022 to 2024). "Parallel to the original discovery of MLIP, the identification of cardiac Isl1-interacting protein (CIP, an alias of MLIP) provided insights into cardiac hypertrophy’s regulatory mechanisms, underscoring its repressive role in cardiomyocyte hypertrophy and downregulation in hypertrophic conditions." (PMID 38994962, 2024).
esophageal cancer (1 paper, 2024). A primary or metastatic malignant neoplasm involving the esophagus. "MLIP was identified as one of seven risk RNAs for esophageal cancer with a hazard ratio of 1.67 (1.22–2.29, p < 0.001)." (PMID 38994962, 2024). "One gene that has emerged as a potential key player in both breast and esophageal cancer is the MLIP gene." (PMID 38994962, 2024). "Finally, according to the recently found role of MLIP in cancer, it has been suggested as a potential biomarker for triple-negative breast cancer and esophageal cancer." (PMID 38994962, 2024).
hypertrophic cardiomyopathy (1 paper, 2022). A condition in which the myocardium is hypertrophied without an obvious cause. "Similarly, MLIP regulates cardiac homeostasis to prevent hypertrophic cardiomyopathy and possibly pulmonary hypertension, two diseases that can result from hypoxia." (PMID 36077479, 2022).
Sepsis (1 paper, 2025). Sepsis is defined as life-threatening organ dysfunction caused by a dysregulated host response to infection. "MLIP-modulated genes were associated with immune-related metabolic pathways in both sepsis and cancer." (PMID 40028316, 2025). "Collectively, these findings highlight MLIP as a pivotal modulator of cellular responses under inflammatory conditions, offering a foundation for its therapeutic potential in managing sepsis and reducing cancer risk associated with inflammation." (PMID 40028316, 2025). "MLIP regulates immune-metabolic dynamics in burn-induced sepsis, influencing macrophage activity and oxidative stress." (PMID 40028316, 2025). "Future research will focus on delineating the specific mechanisms by which MLIP influences sepsis progression, including its roles in inflammatory pathways and effects on cell survival and function." (PMID 40028316, 2025). "This study, through bioinformatics analysis and in vitro cell experiments, has demonstrated the pivotal role of MLIP in burn - induced sepsis." (PMID 40028316, 2025). "Our experiments highlighted MLIP’s potential in regulating immune responses, offering a promising strategy for modulating inflammation in burn-induced sepsis." (PMID 40028316, 2025). "Future research should clarify MLIP’s mechanistic pathways in sepsis and its oncology implications." (PMID 40028316, 2025). "Additionally, it investigates MLIP’s potential involvement in burn-induced sepsis and subsequent cancer progression." (PMID 40028316, 2025). "This study highlights MLIP’s role in burn-induced sepsis as a potential therapeutic target." (PMID 40028316, 2025).
cancer (4 papers, 2020 to 2025). A tumor composed of atypical neoplastic, often pleomorphic cells that invade other tissues. "The focus of this review is to explore the relationship of MLIP with well characterized factors that are associated with the development and progression of cancer." (PMID 38994962, 2024). "However, more research is needed to fully understand MLIP’s role in these cancers and its potential as a therapeutic target or diagnostic tool." (PMID 38994962, 2024). "MLIP is an emerging factor implicated in the regulation of key signaling pathways that govern cell growth, proliferation, survival, and metabolism, which are often dysregulated in cancer." (PMID 38994962, 2024). "Its role in metabolic reprogramming suggests MLIP as a potential therapeutic target linking immune modulation and cancer progression." (PMID 40028316, 2025). "We discuss the current understanding of MLIP’s involvement in pro-survival pathways and its potential implications in cancer cells’ metabolic remodeling and dysregulated homeostasis." (PMID 38994962, 2024). "Such connections suggest a broader role for MLIP in cellular homeostasis and disease, including potential implications in cancer biology." (PMID 38994962, 2024). "This review aims to shed light on MLIP’s potential impact on cancer biology and contribute to developing innovative therapeutic strategies." (PMID 38994962, 2024). "Limited research has focused on elucidating the role of MLIP in the initiation and/or progression of cancer." (PMID 38994962, 2024). "Prognostic analyses revealed MLIP’s impact on survival outcomes across cancer types." (PMID 40028316, 2025). "These molecular relationships underscore how MLIP may have a multifaceted role in maintaining cellular homeostasis and its possible role in cancer progression." (PMID 38994962, 2024). "Additional research is required to directly investigate the involvement of MLIP in cancer biology." (PMID 38994962, 2024). "Understanding MLIP’s regulatory role may offer new insights into cancer treatment strategies, potentially leading to more effective interventions." (PMID 38994962, 2024). "This implies that MLIP might act as a suppressor of cell growth and proliferation, two key processes that are often hyperactivated in cancer." (PMID 38994962, 2024). "Although the precise mechanism through which MLIP increases FOXO-1 expression remains unknown, FOXO-1 is acknowledged for its involvement in cell cycle arrest, apoptosis, and tumor suppression, implying a potential role for MLIP in cancer pathogenesis." (PMID 38994962, 2024). "Therefore, therapies aimed at enhancing MLIP expression or its regulatory effect on the PI3K/Akt/mTOR pathway might be beneficial for inhibiting cancer progression." (PMID 38994962, 2024). "Additionally, we examine the potential of MLIP as a novel therapeutic target for cancer treatment." (PMID 38994962, 2024). "Thus, MLIP deficiency could facilitate these oncogenic processes, suggesting that MLIP might be a novel target for cancer therapy." (PMID 38994962, 2024).
cancer (continued). "This hyperactivation of the Akt/mTOR pathway in the absence of MLIP suggests that MLIP deficiency may accelerate aging in cells and may heighten their susceptibility to tumor development, potentially implicating MLIP in cancer biology." (PMID 38994962, 2024). "Interactions between MLIP and AMPK may hold implications for cancer biology." (PMID 38994962, 2024). "However, functional studies of the other RNAs (LINC01068, LINC00601, AC084262.1, LINC01415, miR-5699-3p, MLIP) have not been reported in cancer research." (PMID 32095316, 2020).
myopathies (3 papers, 2022 to 2025). "Overall, our report of a biallelic nonsense mutation supports the implication of MLIP as a causative gene for myopathies with muscle weakness and hyperCKemia." (PMID 35672413, 2022). "Very recently, an article identified MLIP as disease-causing in a cohort of patients exhibiting early-onset myopathy with rhabdomyolysis." (PMID 35672413, 2022). "Besides myoglobin, the list also included familiar proteins such as LDH and Tropomyosin alpha and included proteins that have been associated with other myopathies in TTN, MLIP and BIN1." (PMID 40110646, 2025).
tumor (3 papers, 2021 to 2025). "We performed RNA sequencing for 30 pairs of TNBC tissue and matched normal tissue from our hospital, and identified five pivotal genes (GALNTL5, MLIP, HMCN2, LRRN4CL, and DUOX2), which were correlated with associated with CD8+ T cell infiltration, tumor progression and therapeutic efficacy." (PMID 35046993, 2021). "Further research on MLIP’s role in immune evasion and tumor metabolism may inform novel therapeutic strategies." (PMID 40028316, 2025).
heart disease (1 paper, 2021). "As mentioned, previous reports suggest that MLIP might play a crucial role in heart disease." (PMID 33452295, 2021).
MLIP also shares sentences with these, for which no sentence is quoted: cardiomyopathy (2 papers); cardiovascular disease (1); Cirrhosis (1); hypertrophy (1); Myalgia (1); ocular hypertension (1); primary open-angle glaucoma (1); pulmonary hypertension (1); schizophrenia (1).